CD4 (CD4 molecule)
Diseases named in the same sentence as CD4 in open-access papers (continued):
Sharing a sentence is not in itself a finding about the gene and the disease.
HIV-1 infection (continued). "Immunological changes in HIV-1 infection include a decrease in CD4+ cells, a transient increase in CD8+ cells, total lymphocytes and inversion of the CD4/CD8 ratio." (PMID 15683549, 2005). "The CD4/CD8 ratio had a >98% sensitivity for diagnosis of HIV-1 infection and a specificity of >98%." (PMID 15683549, 2005). "The authors concluded that CD4/CD8 ratio and %CD4 among lymphocytes are reliable markers of HIV-1 infection in an African pediatric population." (PMID 15683549, 2005). "As described here, we found that a membrane protein, CLDN-7, can serve as a receptor for HIV-1 infection of CD4(-) cells or as a ligand on the viral envelope." (PMID 16368003, 2005). "Stable transfection of the SIV Nef gene in a CD4+ T cell line reduced cell surface-expression of CD4, and rendered the cells resistant to subsequent HIV-1 infection." (PMID 16107223, 2005). "During wild-type HIV-1 infection, insertion of CD4 into HIV-1 envelopes is efficiently blocked by mechanisms that involve the viral Vpu, Nef and Env proteins." (PMID 16371160, 2005). "The main objective of the current study was to evaluate the CD4/CD8 ratio for diagnosis of subtype C HIV-1 infection in infants under the age of 2 years among infants where DNA PCR was performed to diagnose HIV infection." (PMID 15683549, 2005). "Although the effect of GBV-C on HIV-1 infection remains controversial, most studies have shown higher CD4+ cell counts and lower HIV-1 viral loads in GBV-C viremic patients." (PMID 15927079, 2005). "Insertion of cellular ICAM-1, for example, can promote HIV-1 infection of specific cell types such as CD4+ T-lymphocytes and memory CD4+ T cells and will probably influence viral propagation in vivo." (PMID 16371160, 2005). "Consistently, in animal models of HIV-1 infection, monocytes are the major reservoir after acute depletion of CD4-positive T cells." (PMID 15613239, 2004). "Administration of granulocyte-macrophage colony-stimulating factor blunted the viral rebound following interruption of HAART, and largely prevented a decrease of CD4+ T cell counts in an STI trial in chronic HIV-1 infection." (PMID 15526059, 2004). "Comparative data on CD4+ T cell counts in untreated chronic HIV-1 infection were collected by the MACS and analyzed and prepared by Alvaro Muñoz." (PMID 15526059, 2004). "In HIV-1 infection the ongoing depletion of CD4+ T-lymphocytes is believed, to a large extent, to be due to apoptosis." (PMID 18475733, 1996). "However, certain types of cells, such as macrophages and CD4+Foxp3+ regulatory T cells (Tregs), have been shown to resist HIV-1 infection despite co-expressing CD4 and co-receptors." (PMID 42088414, 2026). "Several studies have reported increased OXPHOS during early HIV-1 infection in CD4+ T cells." (PMID 41596493, 2026). "Using two independent methodologies to assess APA in human cell lines and primary CD4+ T cells, we found that HIV-1 infection regulates APA, shaped by the interaction of CPSF6 with the viral capsid, recapitulating the APA phenotype observed in CPSF6 knockout cells." (PMID 41405390, 2026). "Third, HIV-1 captured in blood by DCs (via DC-SIGN) and transported to lymph nodes for antigen presentations and trans-infection of T cells results in faster propagation and dissemination of infecting HIV-1 than direct HIV-1 infection of circulating CD4 + T cells." (PMID 40408432, 2025). "We found that CPSF6 knock-out primary CD4+ T cells are highly permissive to HIV-1 infection." (PMID 41385587, 2025). "Low HIV-1 infection level in the central memory CD4+ T cell subset is a hallmark of both non-progressive HIV infection and non-pathogenetic SIV infection in the natural hosts." (PMID 41244297, 2025). "Previous studies demonstrate that low HIV-1 viral burden in the CM CD4+ T cells correlates with long-term non-progressive HIV-1 infection and is a hallmark of non-pathogenetic SIV infection." (PMID 41244297, 2025).
HIV-1 infection (continued). "We found that HIV-1 infection enhances the METTL3/14 interaction in CD4+ T cells." (PMID 41085277, 2025). "The accumulation of defects in vpr in M-tropic lineages runs counter to the existing literature which suggests that loss of vpr inhibits HIV-1 infection of macrophage, but does not impact infection of CD4+ T cells." (PMID 40950013, 2025). "Similarly, depletion of CPSF6 in primary, resting CD4+ T cells reduced HIV-1 infection in single-round infection assays." (PMID 40202316, 2025). "Thus, it will be intriguing to test how EXOC proteins contribute to HIV-1 infection from CD4+ T cells." (PMID 41292918, 2025). "In this track, we have modified CD4+ target cells with 2P23 peptide, antibody, or bispecific fusion proteins through glycosylphosphatidylinositol anchoring, which can render the cells fully resistant to HIV-1 infection (44, –, 47)." (PMID 40130879, 2025). "Notably, 3-deazaneplanocin A (DZNep), an EZH2 inhibitor, has been proven to effectively activate latent HIV-1 infection in CD4+ T cells and Jurkat T cells (75, –, 78)." (PMID 39692477, 2025). "Moreover, HIV-1 infection leads to a marked reduction in endogenous levels of P-selectin glycoprotein ligand-1 (PSGL-1) in CD4+ T cells." (PMID 40699766, 2025). "Additionally, acute HIV-1 infection is marked by a significant reduction in peripheral CD4+ T-cell counts." (PMID 40003685, 2025). "Interestingly, PLIN3 mRNA accumulated more in the nucleus during HIV-1 infection of primary CD4+ T cells compared with mock controls, whereas the levels of PLIN3 mRNA in the cytoplasm were not significantly different." (PMID 41085277, 2025). "ART initiated in the early stages of HIV-1 infection can slow telomere shortening in CD4+ T cells." (PMID 40244051, 2025). "Our study confirmed that VitD decreases HIV-1 infection in CD4+ T cells." (PMID 40149968, 2025). "Th17 cells, a major CD4+ T cell subset in the FRT, are particularly susceptible to HIV-1 infection." (PMID 41191579, 2025). "We next sought to investigate whether PLIN3 is necessary for HIV-1 infection in primary CD4+ T cells." (PMID 41085277, 2025). "First, low HIV-1 infection burden in the CM CD4+ T cells is a hallmark of non-pathogenetic SIV infection in the natural hosts." (PMID 41244297, 2025). "The intrinsic mechanisms that limit HIV-1 replication in CD4+ T target cells may also play an important role in mediating the resistance of ECs to HIV-1 infection." (PMID 40070826, 2025). "This could explain why we observed fewer changes in 3’ UTR lengths following wild-type HIV-1 infection in primary CD4 + T cells as compared to HT1080 cells and may point to potential cell-type differences in CPSF6 function." (PMID 41385587, 2025). "We next sought to determine whether HIV-1 infection alters the RNA or protein levels of PLIN3 in primary CD4+ T cells." (PMID 41085277, 2025). "Evidence suggests that its expression is related to the depletion of CD4+ T cells in HIV-1 infection, tumor progression in several oncologic diseases through the inhibition of CD4+ T cell differentiation into mature subsets, and tumor cell resistance to the inhibitory control of PD-1." (PMID 39755990, 2025). "Cell-to-cell contact between infected and uninfected cells, as well as cytokines secreted by relevant cells, may influence the sensitivity and infection status of resting CD4+ T cells to HIV-1 infection." (PMID 40650088, 2025). "The steady decline in CD4 + T cells was readily seen in all mice following HIV-1 infection." (PMID 40630517, 2025). "Moreover, enhanced metabolic activity has been suggested to be important for HIV-1 infection as infection increases oxidative phosphorylation and glycolysis in primary CD4+ T cells, whereas oxidative phosphorylation stimulates virus replication." (PMID 39792798, 2025). "Based on our findings that HIV-1 infection promotes m6A methylation of PLIN3 mRNA in CD4+ T cells, we asked whether infection also changes PLIN3 expression in Jurkat CD4+ T cells." (PMID 41085277, 2025).
HIV-1 infection (continued). "However, it is important to define the m6A landscape in primary CD4+ T cells, which are the major target of HIV-1 infection in vivo." (PMID 41085277, 2025). "This discrepancy may be linked to behavioral differences, as previous research has demonstrated that men tend to seek medical care later than women, leading to more advanced HIV-1 infection and consequently lower CD4+ T cell counts." (PMID 39660138, 2024). "In order to identify miRNAs and mRNAs that are modulated upon HIV-1 infection, CD4+ T lymphocytes were isolated from the peripheral blood mononuclear cells (PBMCs) of three blood donors and infected for 48 h with green fluorescent protein (GFP)-marked HIV-1 (CCR5-tropic NL4.3-ADA-GFP)." (PMID 39066239, 2024). "Among other effects, IP-10 has been shown to enhance latent HIV-1 infection of resting CD4+ T cells and monocyte-derived macrophages in vitro by binding to the chemokine receptor CXCR3 and promoting cofilin activity and actin dynamics, thus facilitating HIV-1 entry and DNA integration." (PMID 38790203, 2024). "The anti-MT-C34 chAb can be easily generated using plasmids available for the research community and can serve as a valuable tool for the detection, purification, and even subsequent elimination of HIV-1-resistant CD4 cells or CAR cells engineered to fight HIV-1 infection." (PMID 39336102, 2024). "Subsequent work found SAMHD1 also restricts HIV-1 infection in resting CD4+ T-cells." (PMID 39205287, 2024). "Using a tissue-specific mixed cell infection model, we demonstrate that while no changes in CD14+ macrophage infection susceptibility were observed, CD4+ T cell HIV-1 infection frequency increases following menopause in the EM, but not CX nor ECX." (PMID 39872519, 2024). "The rapid initiation of the antiretroviral therapy (ART) and continuous adherence to it may protect CD4+ T cells from HIV-1 infection and elimination, stabilizing the CD4/CD8 ratio." (PMID 38812512, 2024). "Moreover, HIV-1 infection depletes Mtb-specific Th1/Th17 cells and Th22 CD4+ T cells in human blood and in bronchoalveolar lavage samples." (PMID 39181733, 2024). "Based on our published results, we hypothesize that upon HIV-1 infection of the CD4+ thymocytes, the observed differential regulation of miR-15a and miR-24 that occurs causes abnormal post-transcriptional regulation of specific HOX gene-encoded transcriptomes." (PMID 38721526, 2024). "In a humanized mouse model, CRISPR/Cas9-mediated reduction significantly decreased the surface expression of the CCR5 and CXCR4 co-receptors in primary CD4 + T cells, thereby establishing protection of the cells from HIV-1 infection by R5-tropic, X4-tropic, and dual R5/X4-tropic strains." (PMID 38741006, 2024). "HEAL is upregulated upon HIV-1 infection of macrophages, microglia, and CD4+ T lymphocytes." (PMID 38179937, 2024). "Therefore, effector CD4+ T cells in vivo are expected to be much more permissive to HIV-1 infection since their activated state provides an intracellular environment conducive to the completion of the viral life cycle." (PMID 38580979, 2024). "CD4+ T cells are the primarytarget for HIV-1 infection, and recent studies suggest that memory Tfollicular helper cells within the lymph node, more precisely in the B cellfollicle, harbor integrated provirus, which contribute to viral rebound uponART discontinuation." (PMID 39058091, 2024). "Similarly, our group previously reported that the differential ability of primary HIV-1 Nef to downregulate the HIV-1 receptor CD4 and coreceptor CCR5 is associated with the clinical outcome of HIV-1 infection." (PMID 38279353, 2024). "In combination, these observations provide indirect evidence that increased α4β7 expression frequency is not driving increased EM CD4+ T cell HIV-1 infection susceptibility following menopause." (PMID 39872519, 2024).
HIV-1 infection (continued). "This could explain why we observed fewer changes in 3’ UTR lengths following wild-type HIV-1 infection in primary CD4 + T cells as compared to HT1080 cells." (PMID 39678349, 2024). "Our results demonstrate that the susceptibility of EM derived CD4+ T cells to HIV-1 infection increases post menopause but is unlikely to be driven by increased expression frequency of either CCR5 or integrin-α4β7." (PMID 39872519, 2024). "A drastic decrease in CD4+ T cells is a characteristic of progressive HIV-1 infection." (PMID 38412342, 2024). "Given the critical inhibitory regulatory function of CD59 in CML and the fact that its expression is upregulated during HIV-1 infection of CD4+ T lymphocytes, we examined the impact of CD59 expression on the susceptibility of HIV-1-infected cells and released virions to ADCML." (PMID 39066239, 2024). "Indeed, the percentage of CD32+ CD4 T cells was significantly increased in PBMCs from patients with chronic HIV-1 infection (CHI) compared with healthy donors (HD)." (PMID 38579727, 2024). "The fact that MARCH8 and MARCH2 inhibit HIV-1 infection in different cell types (MDMs vs. CD4+ T cells respectively) may be a reason behind the fact that multiple members of this family of host factors inhibit HIV-1 infection utilizing the same mechanism." (PMID 39074162, 2024). "While macrophages and dendritic cells are more resistant to HIV-1 infection, they are nonetheless productively infected and thus contribute to the pathology associated with AIDS in a number of ways, including facilitating transmission to CD4+ T-cells." (PMID 39205287, 2024). "Therefore, further study is needed to explore how the increased MM affects caspase-1 activated pyroptosis of CD4+T cells in HIV-1 infection, and if the excessive fusion has an effect on it." (PMID 38267841, 2024). "It has been suggested that CD4/CD8 ratio may be useful to monitor HIV-1 infection and to improve clinical decision making." (PMID 38812512, 2024). "We then examined the effect of endogenous MARCH2 on HIV-1 infection in CD4+ T cells and MDMs." (PMID 39074162, 2024). "However, astrocytes can undergo other means of HIV-1 infection such as direct cell-cell transfer via infected CD4+ T cells, whose trafficking in to the CNS has been established." (PMID 39175523, 2024). "Because CD4+ T cells are the primary site of HIV-1 infection, replication, and latency, the use of ARTs that persist at therapeutic concentrations in lymphoid cells could potentially have a positive impact on long-term treatment outcomes." (PMID 39105584, 2024). "However, the role of ATF4 in regulating the death of CD4+ T cells in the context of HIV-1-infection has been poorly explored." (PMID 38534416, 2024). "Similarly, studies have indicated that the utilization of stimulants, such as cocaine, can enhance the likelihood of HIV-1 infection in quiescent CD4+ T cells through σ1R activation." (PMID 39224601, 2024). "We next assessed whether menopausal status alters the susceptibility of CD4+ T cells and CD14+ cells to HIV-1 infection in the FRT mucosa." (PMID 39872519, 2024). "Importantly, a decreased CD4+/CD8+ T cell ratio was observed in the humanized mice following HIV-1 infection, suggesting that our model reproduced similar immunological alterations observed during the natural infection of humans." (PMID 38799434, 2024). "Although the exact mechanisms of CD4+ T-cell loss during HIV-1 infection have not been fully elucidated, recent reports suggest that the Caspase-1–mediated pyroptosis provides the main mechanism." (PMID 39902043, 2024). "Since cell lines are immortalized, they may show different responses to apoptotic or necrotic signaling pathways compared to primary CD4+ cells following HIV-1 infection." (PMID 39459974, 2024).
HIV-1 infection (continued). "Taken together, these results indicate that HIV-1 infection of CD4+ T cells induces the upregulation of CD59 receptor at the mRNA and cell surface protein levels, and this condition appears to be linked to the downregulation of miRNAs, namely miRNAs-21, -26a and 29a, predicted to target CD59." (PMID 39066239, 2024). "In HIV-1 infection, more than 95% of CD4+T cells die of caspase-1 mediated pyroptosis." (PMID 38267841, 2024). "Together, these findings suggest that Vpr may play a role in the transcriptomic remodeling of CD4 + T cells during HIV-1 infection by regulating the DNA methylation of histones." (PMID 38671522, 2024). "Earlier reports of the association of miRNAs expressed by either CD34+ HSPC or CD4+ T-helper cells were not known to be dependent on any role or influence of HIV-1 infection in the context of dys/regulation of hematopoiesis." (PMID 38721526, 2024). "Moreover, also productive HIV-1 infection as assessed by viral reporter gene expression was significantly enhanced in M2-co-cultured CD4 T cells, and HIV-1 fusion efficacy correlated with the extent of receptor CD32 trogocytosis." (PMID 38579727, 2024). "PTEN is expressed in CD4 T cells —the primary targets of HIV-1 infection." (PMID 38400066, 2024). "Taken together, these results suggest that the induction of ATF4 observed in CD4+ T lymphocytes during HIV-1 infection may contribute to the increased production of energy and amino acids required for viral replication." (PMID 38534416, 2024). "Our results show that miRNA-26a expression levels are decreased in CD4+ T cells upon HIV-1 infection, and we provide evidence that this reduction requires the integration of the viral DNA into the genome of target cell, as well as the expression of HIV-1 genes." (PMID 39066239, 2024). "Similarly, mucosal CD4 T-cells, treated with rapamycin, everolimus, or carbamazepine in the context of an ex vivo human HIV-1 infection model, showed increased autophagy activity." (PMID 37446195, 2023). "Similarly to autophagy, xenophagy can restrict HIV-1 infection in productively HIV-1-infected CD4 T-cells by selectively degrading Tat, a protein that is essential for viral transcription and virion production." (PMID 37446195, 2023). "Since it was previously reported that memory CD4+ T cell death during HIV-1 infection is Fas-mediated, and IRF-5 is required for Fas-induced apoptosis, we set out to investigate whether Fas was downstream of IRF-5 in human CD4+ T cells." (PMID 37227774, 2023). "Accordingly, it has been reported that several CD4-negative cells, such as cell lines originating in the nervous system, the intestine and the liver, are susceptible to HIV-1 infection." (PMID 37511488, 2023). "We also investigated whether receptors important for HIV-1 infection of LCs, i.e. CD4, CCR5, and langerin, were affected by LC activation through TLRs." (PMID 36841916, 2023). "Interestingly, in HIV-1 infection, even successfully treated patients demonstrate elevated levels of IL-12, concomitant with a blunting of IL-12-induced in vivo CD4+ T-cell activation." (PMID 37376629, 2023). "Future screening with HIVDEP in other HIV-permissive cell types, most importantly primary CD4+ T cells, may identify other host factors important for HIV-1 infection." (PMID 36744886, 2023). "Over the course of untreated HIV-1 infection, CD4+ T cell levels become depleted." (PMID 37892982, 2023). "HIV-1 infection is characterized by a progressive depletion of circulating CD4+ T cells and by the establishment of a chronic immune activation state marked by a high turnover of T cells, the activation of B cells and T cells, and elevated levels of proinflammatory mediators." (PMID 36853052, 2023). "During an untreated HIV-1 infection, CD4+ T cells are expected to decline over time." (PMID 37161335, 2023).